OR13C3 (olfactory receptor family 13 subfamily C member 3)
Description:
Odorant receptor.
Synonyms: OR37G; OR9-8
Gene: Protein-coding gene on chromosome 9 (104,535,749 to 104,536,856, reverse strand). Ensembl gene ENSG00000204246.
Subcellular location: Cell membrane
Pathways (Reactome):
Sensory Perception: Expression and translocation of olfactory receptors; Olfactory Signaling Pathway
Genetic constraint (gnomAD): Loss-of-function variants: 19 observed, 14.72 expected, observed/expected ratio (o/e) 1.29, 90% interval 0.9 to 1.81. The upper end of that interval is the gene's LOEUF score, 1.81, which puts it in group 6 of 6, group 1 being the genes least tolerant of losing a copy. Missense variants: 374 observed, 384.24 expected, observed/expected ratio (o/e) 0.97, 90% interval 0.89 to 1.06. Synonymous variants: 134 observed, 144.82 expected, observed/expected ratio (o/e) 0.93, 90% interval 0.8 to 1.07.
Homologues: Orthologues: chimpanzee OR13C3 (98% identical), macaque OR13C3 (95% identical), dog OR13C3 (90% identical), pig OR13C3 (89% identical), rabbit OR13C3 (87% identical), mouse Or13c3 (85% identical), rat Or13c3b (85% identical), rat Or13c3c (85% identical), rat Or13c3 (84% identical), rat Or13c3g (84% identical), rat Or13c3e (82% identical), rat Or13c3f (81% identical). Paralogues in human: OR13C4 (84% identical), OR2S2 (66% identical), OR13C8 (65% identical), OR13C2 (64% identical), OR13C9 (64% identical), OR13C5 (63% identical), OR13D1 (57% identical), OR2K2 (55% identical), OR13J1 (48% identical), OR2G3 (48% identical), OR5V1 (48% identical), OR10A7 (47% identical), and 80 more.
Diseases named in the same sentence as OR13C3 in open-access papers:
OR13C3 is named in the same sentence as 2 diseases in open-access papers, as found by Europe PMC text mining. Sharing a sentence is not in itself a finding about the gene and the disease.
OR13C3 shares sentences with these, for which no sentence is quoted: pancreatic tumors (3 papers); pancreatic cancer (2).